TNF (tumor necrosis factor)
Diseases named in the same sentence as TNF in open-access papers (continued):
Sharing a sentence is not in itself a finding about the gene and the disease.
rheumatoid arthritis (continued). "It has been used as immunoglobulin and infliximab, whose target is TNF-α, which is a cytokine that is overexpressed in the inflamed area or even in the blood of patients with autoimmune diseases, such as rheumatoid arthritis." (PMID 33266032, 2020). "Anti‐TNFα therapy is approved to treat many inflammatory diseases, including rheumatoid arthritis, psoriasis and Crohn's disease." (PMID 31737985, 2020). "Inflammatory cytokines such as TNF are major players in pathogenicity and TNF is a major target for treatment, e.g., in rheumatoid arthritis." (PMID 33162973, 2020). "Pursuing this strategy the human anti-TNFα antibody adalimumab, one of the world’s best-selling antibodies for the treatment of immune-mediated inflammatory diseases including rheumatoid arthritis, was chosen to produce the full length of mAbs by A. oryzae." (PMID 32514366, 2020). "Drugs for inhibition of IL-2 and TNF-α are used for autoimmune diseases like rheumatoid arthritis, Crohn’s disease, colitis ulcerosa, or psoriasis." (PMID 32747802, 2020). "In patients with rheumatoid arthritis, TNF‐α and IL‐17A have been shown to promote NET formation contributing to the pathogenesis of the disease." (PMID 32473089, 2020). "The KEGG pathway analysis showed that Cluster 1 is significantly enriched in cytokine-cytokine receptor interaction, influenza A, rheumatoid arthritis, TNF signaling pathway, measles, Herpes simplex infection." (PMID 33362771, 2020). "TNF-α inhibitors are effective when used to treat rheumatoid arthritis and various other autoimmune inflammatory disease states where TNF-α is involved in the pathogenesis." (PMID 33364967, 2020). "Concomitant use of methotrexate (MTX) improves the clinical efficacy of anti-TNF agents in the treatment of rheumatoid arthritis (RA)." (PMID 32922407, 2020). "For initiation and maintenance of defence against Mtb, TNF-α plays a crucial role in reactivation of latent tuberculosis of rheumatoid arthritis patients during the neutralization by the anti-TNF antibody." (PMID 32942991, 2020). "Anakinra was initially approved for the treatment of rheumatoid arthritis with methotrexate in patients that failed treatment on methotrexate alone, but these patients are nowadays prioritized to TNF‐blocking agents." (PMID 32770571, 2020). "The use of anti-TNF antibody treatment is standard nowadays for rheumatoid arthritis and is also of interest for a variety of other autoimmune disease such as Crohn's disease, psoriasis, ulcerative colitis, and ankylosing spondylitis." (PMID 33178579, 2020). "Many clinical trials in patients with rheumatoid arthritis have shown the superiority of MTX in combination with anti-TNF therapy comparing to MTX monotherapy." (PMID 32868798, 2020). "The role of TNF in inflammatory bowel disease and rheumatoid arthritis has been well established both in mouse models and in clinical practice." (PMID 32671059, 2020). "Such approved drugs include inhibitors of TNF-α (e.g., etanercept and adalimumab), IL-6 (e.g., tocilizumab), and IL-1β (e.g., canakinumab) signaling for immune diseases such as rheumatoid arthritis and Crohn’s disease." (PMID 33291425, 2020). "It has been reported previously that excess amounts of TNF-α play a pathological role in several diseases including inflammatory bowel diseases, rheumatoid arthritis, and asthma." (PMID 32382581, 2020). "Our studies also found that KM exerts an anti-inflammatory effect in inflammatory pain and rheumatoid arthritis by inhibiting IL-1β and TNF-α production." (PMID 33542692, 2020).
rheumatoid arthritis (continued). "Adalimumab is a monoclonal antibody directed against tumor necrosis factor-α (TNF-α) and approved for the treatment of rheumatoid arthritis, ankylosing spondylitis, Crohn's disease, ulcerative colitis, plaque psoriasis and other autoimmune diseases." (PMID 32508839, 2020). "Adalimumab, a TNF-α monoclonal antibody drug, has been effective in treating inflammatory diseases such as rheumatoid arthritis, psoriatic arthritis, ankylosing spondylitis, and Crohn’s disease." (PMID 33291425, 2020). "Cimzia® (certolizumab pegol) is a PEGylated anti tumor necrosis factor (TNF) recombinant antibody Fab fragment approved for the treatment of rheumatoid arthritis, Crohn’s disease, and axial spondyloarthritis." (PMID 32117952, 2020). "TNF-α released by activated macrophages can stimulate osteoblast chemotactic effect in vitro, and can inhibit osteoblast differentiation in rheumatoid arthritis patients." (PMID 33415105, 2020). "Tumor necrosis factor (TNF) is an essential cytokine for the maintenance of host defense during human tuberculosis (TB), as patients with rheumatoid arthritis often develop TB reactivation during anti-TNF therapy." (PMID 32922385, 2020). "In 1998, the first monoclonal antibody therapy targeting tumor necrosis factor (TNF), a cytokine that plays an important role in rheumatoid arthritis pathogenesis, was approved." (PMID 32944095, 2020). "We previously demonstrated that patients with rheumatoid arthritis or ankylosing spondylitis treated with anti–TNF-α drugs have increased frequencies of IL-10+ CD4+ T cells in peripheral blood." (PMID 32321757, 2020). "In rheumatoid arthritis, inflammatory cytokines such as TNF increase RANKL expression in synoviocytes and subsequently promote osteoclastic differentiation and activation, resulting in erosive bone changes in joints." (PMID 32532031, 2020). "The adjuvant-induced arthritis (AIA) rats, widely accepted as rheumatoid arthritis experimental model, were constructed to evaluate the bifunctions of the recombinant anti-TNF-α fusion proteins (FVH1-1) in vivo." (PMID 32880389, 2020). "It is known that proinflammatory cytokines, such as TNF-α, can expand the number of osteoclast precursors in inflammatory models of rheumatoid arthritis." (PMID 32471111, 2020). "Here we investigated the role of mouse TNF-α on the AD-like phenotype of 5XFAD mice using a knock-in mouse with deletion of the 3’UTR of the endogenous TNF-α (TNFΔARE/+) that develops rheumatoid arthritis and Crohn’s disease." (PMID 32457323, 2020). "IL-1, IL-6, and tumor necrosis factor α (TNFα) play a major pathological role in rheumatoid arthritis through NF-ĸB and JAK/STAT pathways." (PMID 32079226, 2020). "The KEGG pathway analysis results demonstrated that DEGs were particularly enriched in cytokine-cytokine receptor interaction, TNF signaling pathway, chemokine signaling pathway, pertussis, and rheumatoid arthritis." (PMID 33144895, 2020). "Infliximab is a monoclonal antibody against TNF-α approved for treatment of rheumatoid arthritis, Crohn’s disease and other immune-mediated inflammatory disorders." (PMID 33343293, 2020). "For the anti-tumor necrosis factor (anti-TNF) antibodies used in rheumatoid arthritis, although there is an initial loading dose to reduce an existing inflammatory signal, the long-term use is to provide prophylaxis against relapse." (PMID 31999695, 2020). "Anti-TNF- α agents are used in the treatment of autoimmune diseases, like rheumatoid arthritis and inflammatory bowel disease." (PMID 32982743, 2020). "Infliximab is a chimeric monoclonal antibody (mAb) blocking the effect of tumor necrosis factor alpha (TNF-α) which has been widely used since 1999 for treatment of a number of inflammatory rheumatic diseases including rheumatoid arthritis (RA)." (PMID 32793189, 2020).
rheumatoid arthritis (continued). "These different genes involved into 55 down‐ regulated pathways were identified, including IL‐17 signaling pathway, legionellosis, cytokine‐cytokine receptor interaction, rheumatoid arthritis, TNF signaling pathway, and so on." (PMID 32249461, 2020). "TQ also inhibits the inflammatory effects of the proinflammatory cytokine TNF-α by activation of p38/JNK via apoptosis-regulated signaling kinase 1 in rheumatoid arthritis synovial fibroblasts." (PMID 32793594, 2020). "Adalimumab is a subcutaneously administered biological disease modifier used for the treatment of rheumatoid arthritis and other TNFα-mediated chronic debilitating diseases." (PMID 31894001, 2020). "Scavenging antibodies and antigen-binding fragments (Fab) against TNF-α have proven to successfully suppress TNF-α-mediated inflammation in inflammatory autoimmune diseases including rheumatoid arthritis, psoriasis, and Crohn’s disease." (PMID 32518229, 2020). "Tumour necrosis factor (TNF)-α is a key mediator of inflammation in rheumatoid arthritis, and its discovery led to the development of highly successful anti-TNF therapy." (PMID 31581724, 2019). "To date, resveratrol (stilbenes grape) also inhibits TNF-alpha-induced MMP-3 production in human rheumatoid arthritis fibroblast-like synoviocytes via a modulation of the PI3kinase/Akt pathway." (PMID 31888255, 2019). "The association between inflammation and dysregulated bone remodeling is apparent in rheumatoid arthritis and is recapitulated in the human tumor necrosis factor transgenic (hTNFtg) mouse model." (PMID 31777818, 2019). "TNF inhibiting drugs are powerful and popular, and they revolutionized the treatment of rheumatoid arthritis, Crohn disease, and psoriasis." (PMID 31787972, 2019). "TNF is a cytokine critical for the development and progression of arthritis, as shown by progressive arthritis in murine TNF-transgenic mice, and dramatic therapeutic effect of TNF inhibitors on human rheumatoid arthritis." (PMID 31052273, 2019). "SHW administration improved the various features of arthritis and rheumatoid arthritis including elevated serum levels of IL-6, TNF-alpha, type II collagen IgG, swelling of hind limbs, and infiltration of inflammatory cells in the synovial membrane." (PMID 30606189, 2019). "Anti-TNF-α agents have been shown to induce IL-17 expression in CD4 T cell from patients with juvenile idiopathic arthritis or rheumatoid arthritis." (PMID 31475008, 2019). "In another study using a rheumatoid arthritis model of inflammation induced by LPS in vitro, hyperoside has demonstrated a significant (concentration-dependent) effect on inhibition of TNF-α, IL6 and IL-1β." (PMID 31405193, 2019). "MMP-3 was significantly reduced by the addition of adalimumab therapy in patients with rheumatoid arthritis and by TNF-α antagonist therapy (infliximab, etanercept, and adalimumab) in patients with spondyloarthritis." (PMID 31686457, 2019). "This study profiled genome-wide CNVs in Korean patients with rheumatoid arthritis (RA) to investigate the efficacy of treatment with TNF-α blockers." (PMID 31462329, 2019). "In human inflammatory diseases, such as rheumatoid arthritis, inhibiting TNF-α with anti-TNF-α antibodies or sTNFR-fusion proteins has been gaining increasing attention as a promising treatment strategy." (PMID 30819151, 2019). "For example, a French study in adults with rheumatoid arthritis demonstrated that 76% of patients reduced their PRD use during the first 3 months of anti-TNF therapy, and 15% discontinued PRD use altogether." (PMID 31500631, 2019). "Tumor necrosis factor inhibitor therapy for rheumatoid arthritis (RA) patients reduces disease activity, but little is known about the factors that correlate with continuation of remission." (PMID 30956738, 2019).
rheumatoid arthritis (continued). "A study on rheumatoid arthritis also showed that incubating THP-1 with TNF-α inhibitors can suppress the MCP1 gene activation by reducing the recruitment of histone acetyltransferases in the promoter region of the MCP1 gene." (PMID 31737059, 2019). "Investigations in the field of Rheumatoid Arthritis and other degenerative bone diseases describe a special role for TNF-α in the interplay of bone destruction upon chronic inflammation." (PMID 31831031, 2019). "ETA, a fusion protein of the TNF receptor and IgG1 Fc, and a widely used clinical TNF-α inhibitor in rheumatoid arthritis, was used in our model to block the effects of TNF-α." (PMID 31170164, 2019). "For instance, a study detected US synovitis of wrist joints in 50 early rheumatoid arthritis patients, and disclosed PD-US synovitis showed positive correlation with TNF-α, IL-6, and angiopoietin-1 and -2 levels." (PMID 31778437, 2019). "The most significantly enriched pathways in both models included cytokine–cytokine receptor interactions, chemokine signaling pathways, NF-κB pathway, rheumatoid arthritis signaling, and phagosome and TNF signaling pathway." (PMID 31184997, 2019). "Tumor necrosis factor alpha (TNF-α) blockers are widely used in numerous inflammatory diseases such rheumatoid arthritis, psoriasis or inflammatory bowel diseases." (PMID 31469834, 2019). "Infliximab (IFX) is an anti-tumor necrosis factor (TNF)-alpha chimeric monoclonal antibody used in the management of autoimmune inflammatory disorders such as rheumatoid arthritis (RA), psoriasis, Crohn’s disease, and inflammatory bowel disease (IBD)." (PMID 31608149, 2019). "Intracellular signaling pathway (including TNF signaling) play a critical role in rheumatoid arthritis." (PMID 31608109, 2019). "The objective of this study was to evaluate the cost-effectiveness of abatacept, tocilizumab, and tumor necrosis factor (TNF) inhibitors as compared with rituximab in Finnish rheumatoid arthritis patients, who have previously been treated with TNF inhibitors." (PMID 31339961, 2019). "In this line of thought, it has also been reported that this ratio is an indicator of the activity of another arthritis disease, rheumatoid arthritis (RA), and can monitor the anti-inflammatory effects of TNF-⍺ in those patients." (PMID 31694709, 2019). "Among the biological agents approved for the treatment of rheumatoid arthritis are those that act as TNF-α antagonists, called anti-TNF-α." (PMID 30818882, 2019). "There is considerable evidence suggesting a relationship between overproduction of TNF-α and chronic inflammatory diseases such as rheumatoid arthritis, psoriatic arthritis, psoriasis, or inflammatory bowel disease." (PMID 31461974, 2019). "In this context, common treatment strategies involving modulation of TNF-α proved to be quite effective against bone resorption in rheumatoid arthritis." (PMID 31831031, 2019). "The development of anti-TNF therapies has been a milestone in the treatment of rheumatoid arthritis." (PMID 31071076, 2019). "In our patient, AHA occurred during tumor necrosis factor alpha (TNF-α) inhibitor treatment for rheumatoid arthritis." (PMID 30828175, 2019). "The TNF inhibitor golimumab (GLM) is a treatment option in patients with rheumatoid arthritis (RA), psoriatic arthritis (PsA), and ankylosing spondylitis (AS)." (PMID 30415451, 2019). "A patient-level simulation model was developed to predict costs and outcomes associated with four biological drugs (abatacept, tocilizumab, rituximab and TNF inhibitors) in the treatment of rheumatoid arthritis." (PMID 31339961, 2019). "In rheumatoid arthritis (RA), M1 macrophages secrete pro-inflammatory cytokines, such as tumor necrosis factor- (TNF-α) and interleukin-1." (PMID 31370273, 2019). "Etanercept is a widely used biological agent in the treatment of autoimmune diseases such as rheumatoid arthritis, psoriasis, and others by targeting TNF-α." (PMID 31781229, 2019).
rheumatoid arthritis (continued). "Here we investigate the mechanisms by which its synergistic interactions with TNFα regulate the cellular bioenergetics and invasive function of synovial cells from patients with Rheumatoid Arthritis." (PMID 31555281, 2019). "TNF-α antagonist, etanercept, is widely used for the treatment of inflammatory diseases, including rheumatoid arthritis, axial spondyloarthritis, psoriatic arthritis, and plaque psoriasis." (PMID 31758072, 2019). "The introduction of TNFα inhibitors has significantly improved the outcomes of rheumatoid arthritis (RA) treatment." (PMID 30675683, 2019). "Tumor necrosis factor-alpha (TNFα) inhibitors have significantly improved the outcomes of treatment for rheumatoid arthritis (RA)." (PMID 30675683, 2019). "Anti-TNF biologics are widely-prescribed and efficacious in rheumatoid arthritis, ankylosing spondylitis, inflammatory bowel disease, and psoriasis." (PMID 32232095, 2019). "The KEGG pathway enrichment showed that IL-6 was enriched in rheumatoid arthritis, cytokine-cytokine receptor interaction, and TNF signaling pathway." (PMID 31139654, 2019). "Inhibition of mTOR has been demonstrated to halt osteoclastogenesis and to improve joint erosions in a TNF-transgenic mice model of rheumatoid arthritis." (PMID 32194539, 2019). "Patients with rheumatoid arthritis and plaque psoriasis taking prescribed etanercept, which is a TNF-α antagonist, reported significant reductions in depressive symptoms." (PMID 30804748, 2019). "In patients with rheumatoid arthritis, serum levels of chemerin were reduced by anti-TNF therapy, indicating its possible involvement in inflammation." (PMID 31781638, 2019). "Anti-tumor necrosis factor alpha (anti-TNF) treatments are prescribed for people with rheumatoid arthritis according to specific recommendations by the National Institute for Health and Care Excellence in England." (PMID 31891115, 2019). "Tumor necrosis factor inhibitors (TNFi) have become the cornerstone for the treatment of rheumatoid arthritis and other systemic autoimmune conditions." (PMID 30891325, 2019). "TNF has a pivotal role in response to infections and in the pathogenesis of different immune-mediated disorders, like rheumatoid arthritis (RA) and spondyloarthritis (SpA)." (PMID 31881890, 2019). "Signs of inflammation in cerebrospinal fluid (CSF) of rheumatoid arthritis patients correlate positively with fatigue, a central nervous system (CNS)-related symptom that can be partially suppressed by TNF blockade." (PMID 30770760, 2019). "Recently, it has been reported that the single nucleotide polymorphisms (SNPs) of STAT4, PTPN2, PSORS1C1, and TRAF3IP2RA genes are associated with the clinical efficacy of tumor necrosis factor (TNF) inhibitors in the treatment of rheumatoid arthritis (RA) patients." (PMID 31709198, 2019). "A clinical study on patients with rheumatoid arthritis showed a significant reduction in ADMA after 3 months of treatment with TNF-α inhibitors by increasing endothelial progenitor cells." (PMID 31607906, 2019). "TNF-α is a key mediator in the pathological mechanisms underlying many neurological disorders, including ALS, and autoimmune disorders such as rheumatoid arthritis, ankylosing spondylitis, and Crohn’s disease." (PMID 31752240, 2019). "Bioelectronic devices targeting the inflammatory reflex reduce TNF and inflammation in preclinical models of inflammatory disease, and in patients with rheumatoid arthritis and Crohn’s disease." (PMID 32232095, 2019). "Most notable are Infliximab and Adalimumab, which block the critical cytokine tumor necrosis factor-α (TNF-α) in Crohn's disease and rheumatoid arthritis, respectively." (PMID 31001278, 2019). "Clearly, TNF blockers have been a game-changer for the treatment of inflammatory diseases such as rheumatoid arthritis and colitis showing high response rates in many patients making them the commercially most successful biologicals on the market." (PMID 31555271, 2019).